N4BP1 (NEDD4 binding protein 1)
Diseases named in the same sentence as N4BP1 in open-access papers:
N4BP1 is named in the same sentence as 27 diseases in open-access papers, as found by Europe PMC text mining. Sharing a sentence is not in itself a finding about the gene and the disease. The quoted sentences say what the papers report.
neuroblastoma (5 papers, 2019 to 2024). Neuroblastoma (NB) is the most common solid, extracranial childhood tumor. "In a previous publication, by mapping the N4BP1-associated proteins using mass spectrometry, LUC7L3 was associated with N4BP1 in neuroblastoma cells (original data obtained from Professor Boes)." (PMID 39491646, 2024). "We have previously identified two major negative regulators of MHC-I via NFkB signaling in neuroblastoma: Nedd4 Binding Protein 1 (N4BP1) and TNFα-induced protein 3 interacting protein 1 (TNIP1)." (PMID 32630675, 2020). "Accordingly, by interacting with the de-ubiquitinating enzyme Cezanne, N4BP1 acts also as a potent negative regulator of nuclear factor-kappa B (NF-κB) signaling in neuroblastoma cells, a role that points to N4BP1 as a candidate target for immunotherapy." (PMID 31319543, 2019).
viral infection (3 papers, 2018 to 2025). "On the other hand, the highest peak for the Homabay population was associated with N4BP1, an interferon stimulated gene that has been shown to be important during viral infections." (PMID 29357367, 2018). "Thus, we hypothesized that 3Cpro targets N4BP1 for cleavage to relive N4BP1-mediated inhibition of NF-κB signaling, which may enhance the inflammatory response caused by viral infection." (PMID 39655957, 2025). "Our data show that multiple 3Cpros cleave N4BP1 at residue Q816 and that cleavage of endogenous N4BP1 can occur during viral infection." (PMID 39655957, 2025). "Together, N4BP1 cooperates with MCPIP1 to suppress specific virus infection, including HIV-1 and PRRSV." (PMID 35467421, 2022). "We aimed to confirm that 3Cpro-mediated cleavage of N4BP1 occurs in the context of viral infection." (PMID 39655957, 2025). "Our biochemical assays showed that human N4BP1 is targeted by 3Cpro for cleavage at glutamine 816 (Q816), which impairs its regulatory function in tumor necrosis factor alpha (TNFα)-triggered NF-κB-related inflammatory signaling but does not affect viral infection in tissue culture." (PMID 39655957, 2025).
hepatocellular carcinoma (2 papers, 2019 to 2025). A malignant tumor that arises from hepatocytes. "In a library of 132 RBPs with known RNA-binding domains such as RNA recognition motif domains or zinc finger domains, we found that N4BP1 inhibited HBV replication, was negatively correlated with HBV core-associated HBV DNA levels in hepatoma cell lines and suppressed HBV replication." (PMID 40111401, 2025). "In hepatocellular carcinoma cell lines transfected or infected with HBV, the overexpression of N4BP1 decreased core-associated HBV DNA levels, while knockdown or knockout of the gene encoding N4BP1 rescued core-associated HBV DNA levels." (PMID 40111401, 2025). "Although N4BP1 expression has been reported to be induced by type I IFN, the stimulation of N4BP1 expression by IFN-α (type I IFN) and IFN-λ (type III IFN) treatment varied between the PHHs and hepatoma cell lines we tested." (PMID 40111401, 2025). "In characterizing N4BP1 expression, we found that N4BP1 expression was not induced by HBV infection or transfection in hepatoma cell lines." (PMID 40111401, 2025).
ovarian carcinoma (2 papers, 2019 to 2022). A malignant neoplasm originating from the surface ovarian epithelium. "In the process of ovarian cancer development and progression, miR-28-5p downregulates N4BP1, forces cancer cells to enter S phase, and promotes ovarian cancer cell proliferation and invasion." (PMID 31921670, 2019). "Besides, the miR-28-5p induced the arrest of ovarian cancer cells in the S-phase by down-regulating N4BP1 along with promoting their proliferation and invasion." (PMID 35873635, 2022).
enterovirus infection (1 paper, 2025). "N4BP1 is a multifunctional protein with diverse roles in regulating ubiquitination, signal transduction, protein‒protein interactions, and immune responses (36, –, 39, 41, 42, 44, 45), but its role in enterovirus infection is poorly understood." (PMID 39655957, 2025). "In addition to the regulation of NF-κB signaling, further studies are needed to determine the effects of 3Cpro-induced cleavage of N4BP1 fragments in the context of enterovirus infection." (PMID 39655957, 2025).
esophageal carcinoma (1 paper, 2026). A primary or metastatic malignant neoplasm involving the esophagus. "Among the analyzed tumor types, N4BP1 showed the highest expression in kidney chromophobe (KICH), head and neck squamous cell carcinoma (HNSCC), and esophageal carcinoma (ESCA)." (PMID 41513619, 2026).
head and neck cancer (1 paper, 2026). A primary or metastatic malignant neoplasm affecting the head and neck. "The results in cell lines are similar to those in cancer tissues, with higher N4BP1 expression observed in cell lines derived from head and neck cancers." (PMID 41513619, 2026).
head and neck squamous cell carcinoma (1 paper, 2026). A squamous cell carcinoma that arises from any of the following anatomic sites: lip and oral cavity, nasal cavity, paranasal sinuses, pharynx, larynx, and salivary glands. "N4BP1 exhibits the highest expression in head and neck squamous cell carcinoma among all analyzed cancer types." (PMID 41513619, 2026). "In summary, N4BP1 shows the highest expression in head and neck squamous cell carcinoma, with its level elevated in tongue cancer tissues relative to adjacent non-neoplastic tissues." (PMID 41513619, 2026).
Hyperkeratosis (1 paper, 2021). Hyperkeratosis is a histopathological term defining a thickened stratum corneum and may be present in many different skin conditions, with many possible overlaps. "Consistent with a role of N4BP1 in psoriasis, the hyperkeratosis, parakeratosis and acanthosis were more pronounced in KO mice compared to that in WT control mice." (PMID 33990547, 2021).
Immunodeficiency (1 paper, 2022). Failure of the immune system to protect the body adequately from infection, due to the absence or insufficiency of some component process or substance. "Besides, caspase-8 mutation in humans causes immunodeficiency in addition to ALPS, which can be explained by the mechanisms that caspase-8 cleaves and inactivates a cytokine production suppressor NEDD4-binding protein 1 (N4BP1)." (PMID 35064213, 2022).
oral cancer (1 paper, 2026). "Transcriptome profiling identified CCL2 and GM-CSF as downstream targets of N4BP1 in oral cancer." (PMID 41513619, 2026). "N4BP1 is an endoribonuclease that specifically regulates a subset of mRNA targets (including CCL2 and GM-CSF) and plays an essential role in oral cancer." (PMID 41513619, 2026).
oral squamous cell carcinoma (1 paper, 2026). "Here, by using N4BP1-deficient mice, we demonstrated a pivotal role of N4BP1 in the development of oral squamous cell carcinoma." (PMID 41513619, 2026). "Due to the critical role of N4BP1 in oral squamous cell carcinoma, it might be a very promising druggable target for treatment." (PMID 41513619, 2026).
periodontitis (1 paper, 2026). An acute or chronic inflammatory process that affects the tissues that surround and support the teeth. "Modulating N4BP1 or its downstream pathways may represent a potential precision therapeutic strategy for periodontitis and related inflammatory diseases, pending further interventional validation." (PMID 42292374, 2026).
psoriasis (1 paper, 2021). An autoimmune condition characterized by red, well-delineated plaques with silvery scales that are usually on the extensor surfaces and scalp. "Loss of N4BP1 results in increased segmented neutrophil in blood and contributes to the development of psoriasis." (PMID 33990547, 2021). "They observed that the N4BP1-deficient mice developed exacerbated psoriasis with more epidermal hyperplasia, inflammatory cell infiltration, and serum CXCL1 level compared to WT mice." (PMID 33990547, 2021). "Here, we independently established the N4BP1 knockout mice and performed detailed analysis to uncover the role of N4BP1 in psoriasis." (PMID 33990547, 2021). "Further studies on the detailed regulatory mechanism of how N4BP1 specifically recognizes its targets and its relationship with Regnase-1 should provide additional insights into the pathogenesis of psoriasis." (PMID 33990547, 2021). "It suggests that N4BP1 is a novel regulator in psoriasis and its functional is independent on overproduction of TNFa, IL-23, and IL-17." (PMID 33990547, 2021). "Our study on the expression of N4BP1 showed that N4BP1 has a highly expression in skin and indicated a function in psoriasis." (PMID 33990547, 2021). "The back-to-back investigations performed by two groups support the important role of N4BP1 in psoriasis." (PMID 33990547, 2021). "In IMQ-induced psoriasis model, we found N4BP1 knockout mice developed severe psoriasis due to abnormal keratinocyte proliferation and neutrophil infiltration." (PMID 33990547, 2021). "N4BP1 acts as a nuclear ribonuclease to take charge of keratinocytes and neutrophils, and its abnormality contributes to psoriasis development, presenting it as a potential therapeutic target to treat psoriasis." (PMID 33990547, 2021). "Taken together, loss of N4BP1 results in not only abnormal keratinocyte proliferation but also abnormal neutrophil maturation and infiltration by directly controlling JunB, FosB, and CXCL1, respectively, leading to susceptibility to psoriasis." (PMID 33990547, 2021). "To assess whether N4BP1 plays a role in psoriasis, we treated the back skin of WT and KO mice with IMQ, a common medicine used to induce psoriasis in mice." (PMID 33990547, 2021). "Collectively, N4BP1 negatively regulates IMQ-induced psoriasis in vivo." (PMID 33990547, 2021). "It suggests that the severe psoriasis observed in N4BP1-deficient mice is not due to overproduction of TNFa, IL-23, and IL-17." (PMID 33990547, 2021). "They established the N4BP1 knockout mice and examined the response of these mice under IMQ-induced psoriasis model." (PMID 33990547, 2021). "To further examine the expression of N4BP1, we established the imiquimod (IMQ)-induced psoriasis in mice." (PMID 33990547, 2021). "Our results indicate that N4BP1 plays critical and nonredundant role in psoriasis via controlling the function of keratinocytes and neutrophils." (PMID 33990547, 2021). "To understand the molecular mechanism of N4BP1 in the regulation of neutrophil infiltration, we examined the mRNA level of several key genes involved in inflammation including TNFa, IL-23, IL-17, CXCL1, CCL20, S100A8, and S100A9 in psoriasis skin from N4BP1 KO and WT mice." (PMID 33990547, 2021). "Here, we unraveled another member that is N4BP1, plays critical role both in keratinocytes and neutrophils by directly controlling mRNA stability of several key genes including JunB, FosB, and CXCL1, and through such mechanism maintains skin hemostasis to prevent the development of psoriasis." (PMID 33990547, 2021).
squamous cell carcinoma (1 paper, 2026). A carcinoma arising from squamous epithelial cells. "Here, we found that N4BP1 is critical for epithelial cells transformation to squamous cell carcinoma." (PMID 41513619, 2026). "Given that tongue (oral) squamous cell carcinoma is one of the most frequent subtypes in HNSCC, we examined the expression of N4BP1 in control human oral keratinocyte (HOK) cell line and two tongue squamous cell carcinoma cell lines (SCC9 and CAL27)." (PMID 41513619, 2026).
tongue cancer (1 paper, 2026). A malignant neoplasm affecting the tongue. "To understand the underlying mechanism of N4BP1 up-regulation in tongue cancers, we treated SCC9 and CAL27 cells with super-enhancer inhibitors." (PMID 41513619, 2026). "Furthermore, the increased N4BP1 in tongue cancer is associated with super-enhancers." (PMID 41513619, 2026). "Collectively, our in vivo model, coupled with single-cell analysis, unequivocally underscores the essential role of N4BP1 in facilitating the progression of 4-NQO-induced tongue cancer." (PMID 41513619, 2026). "Furthermore, the up-regulation of N4BP1 in tongue squamous carcinoma was validated in three tongue cancer tissues isolated from patients." (PMID 41513619, 2026). "Our results demonstrate that N4BP1 is an essential gene in tongue cancer development." (PMID 41513619, 2026). "Immunohistochemistry and western blotting also show the increased expression of N4BP1 in tongue cancer tissues compared to adjacent non-neoplastic tissues." (PMID 41513619, 2026).
tongue squamous cell carcinoma (1 paper, 2026). A squamous cell carcinoma that arises from the tongue. "In summary, our study utilizing a genetic mouse model and single-cell sequencing has elucidated the critical role of N4BP1 in the progression of tongue squamous cell carcinoma." (PMID 41513619, 2026). "The increased level of N4BP1 in tongue squamous cell carcinoma (TSCC) suggests that it may play a crucial role in the progression of TSCC." (PMID 41513619, 2026).
tumor (5 papers, 2012 to 2026). "As shown, M1 macrophage markers-including IL-1β, IL-6, iNOS, and TNFα-were significantly increased in THP-1 cells co-cultured with N4BP1-deficient TSCC cells compared to those co-cultured with control tumor cells." (PMID 41513619, 2026). "Consistent with observed tumor nodules, both the number and proportion of cancerous cells were significantly reduced in N4BP1-deficient mice compared to wild-type mice." (PMID 41513619, 2026). "Due to the critical role of CCL2 and GM-CSF in macrophage recruitment and differentiation, we culture control and N4BP1-deficient tumor cell with activated THP-1 cells." (PMID 41513619, 2026). "Compared to control cells, N4BP1-deficient TSCC cells formed substantially smaller tumor masses." (PMID 41513619, 2026). "Consistently, N4BP1-deficient SCC9 and CAL27 tumor tissues exhibited increased CCL2 expression along with increased M1 macrophage marker, iNOS." (PMID 41513619, 2026). "N4BP1 regulates multiple facets of cancer development, influencing not only cancer cells themselves but also the tumor microenvironment." (PMID 41513619, 2026). "In tumor tissues established in vivo, the levels of CCL2 and GM-CSF were also significantly up-regulated in N4BP1-deficient tumors compared to controls, as examined by RT-PCR, western blotting (WB), immunohistochemistry (IHC), and immunofluorescence (IF)." (PMID 41513619, 2026). "Here, we reported that N4BP1, a sequence-specific endoribonuclease, plays a very important role in both tumor cell growth and immune evasion." (PMID 41513619, 2026). "Given that CCL2, GM-CSF, and CXCL8 primarily function within the tumor microenvironment, we expected that other N4BP1 targets might directly affect cancer cells." (PMID 41513619, 2026). "N4BP1 not only broadly affects cancer cells but also controls the tumor microenvironment." (PMID 41513619, 2026). "Thus, our results demonstrated that CCL2 and GM-CSF are key downstream targets of N4BP1 for establishment tumor-suppressive immune microenvironment." (PMID 41513619, 2026). "Our results suggest that N4BP1 controls multiple targets, such as CCL2, GM-CSF, CXCL8, and S100A2, to regulate multiple tumor malignant behaviors." (PMID 41513619, 2026). "In-silico analysis showed that several genes (CASZ1, IL1RAPL1, SOX17, N4BP1 and ARHGDIA) suggested to have tumor suppressive functions were target genes of miR-151." (PMID 22928040, 2012). "In N4BP1 knockout mice, the epidermal tissue exhibited dysplasia but did not form tumor nodules." (PMID 41513619, 2026).
cancer (4 papers, 2017 to 2026). A tumor composed of atypical neoplastic, often pleomorphic cells that invade other tissues. "Apart from its intrinsic role in cancer cells, N4BP1-deficient cancer cells induce the differentiation of macrophages into the M1 phenotype." (PMID 41513619, 2026). "Upon 4-NQO induction, only very few N4BP1-deficient epithelial cells are transformed to carcinoma, and most of them are blocked at dysplasia stage." (PMID 41513619, 2026). "Single-cell profiling demonstrated that N4BP1-deficient epithelial cells arrest at an early stage of cancerous transformation, while wild-type epithelial cells efficiently progress to an advanced stage of cancer." (PMID 41513619, 2026). "Notably, the N4BP1-deficient mice develop and grow normally, suggesting that disruption of N4BP1 may significantly impede cancer development while having minimal adverse effects on patients." (PMID 41513619, 2026). "However, the role of N4BP1 in other cancers and its underlying mechanisms are unknown." (PMID 41513619, 2026). "N4BP1 is a novel endoribonuclease that targets on mRNA coding sequences and plays a critical role in inflammatory response, but its role in cancer is unclear." (PMID 41513619, 2026). "N4BP1 is a sequence-specific endoribonuclease that involved in multiple aspects during cancer development." (PMID 41513619, 2026). "N4BP1 not only drives cancer cell evolution but also establishes an immune-suppressive microenvironment." (PMID 41513619, 2026). "To elucidate the potential role of N4BP1 in cancer, we conducted a comprehensive analysis of N4BP1 transcript levels across 21 different cancer types using data from the TCGA database." (PMID 41513619, 2026). "In established human cancer cell lines, N4BP1 also plays a crucial role in proliferation, migration, colony formation, and in vivo growth." (PMID 41513619, 2026). "To avoid tissue complexity, we also analyzed N4BP1 level in cancer cell lines by using the CCLE dataset." (PMID 41513619, 2026). "Among the enriched targets that are more strongly associated with cancer (i.e., RAP1B, N4BP1, MAPK1, and E2F6), almost all are protumoral." (PMID 29085832, 2017). "N4BP1 specifically degrades a subset of mRNA targets through their coding sequences and functions as a negative regulator of inflammation; however, its role in cancer development remains undefined." (PMID 41513619, 2026). "By mRNA profiling, we found that these cytokines, including CCL2, GM-CSF, and CXCL8, might be important downstream targets of N4BP1 in establishing the cancer microenvironment." (PMID 41513619, 2026). "However, whether S100A2 is the central player downstream of N4BP1 in cancer cells remains to be explored." (PMID 41513619, 2026). "Indeed, downregulation of ENTREP is seen in various types of cancer, whereas NDFIP1, NDFIP2, and N4BP1 are infrequently downregulated (Fig EV4A)." (PMID 34927784, 2022).
infection (3 papers, 2024 to 2025). The state of being infected such as from the introduction of a foreign agent such as serum, vaccine, antigenic substance or organism. "Western blot analysis of infected whole lung tissue confirmed that N4BP1 was cleaved during infection, and this cleavage was dependent on caspase-8 and TNF." (PMID 41233351, 2025). "The cells were infected with CVB3–GFP at a multiplicity of infection (MOI) of 5, and N4BP1 cleavage was assessed by Western blotting." (PMID 39655957, 2025). "A reduction in the level of N4BP1 and the cleavage product was observed in HeLa-sgNT cells during CVB3–GFP infection." (PMID 39655957, 2025).
N4BP1 also shares sentences with these, for which no sentence is quoted: Autoimmunity (1 paper); breast carcinoma (1); chronic hepatitis B (1); gastric cancer (1); meningioma (1); renal cell carcinoma (1); rheumatoid arthritis (1).